BRAF (B-Raf proto-oncogene, serine/threonine kinase)
Diseases named in the same sentence as BRAF in open-access papers (continued):
Sharing a sentence is not in itself a finding about the gene and the disease.
tumor (continued). "Several clinicopathological characteristics, including age at diagnosis, tumor location, and patient survival, differ between patients with MLH1-deficient/BRAF-V600E–mutated dMMR CRC and those with MLH1-deficient/BRAF wild-type dMMR CRC." (PMID 36618386, 2022). "The overall tumor mutation burden of ATC is greater than other types of TC, with BRAF and RAS oncogenes, which are components of the RAS-to-ERK signaling pathway, being the main drivers." (PMID 36612173, 2022). "The well-known driver genes (BRAF, RAS) belonging to MAPK or PI3K pathways harbored the naturally occurring mutations and were commonly mutated across tumor stages." (PMID 35996174, 2022). "As an inclusion criterion for our analysis, all 135 patients had shown tumor progression upon initial CPI or BRAF ± MEKi treatment, which required the administration of subsequent tumor treatments." (PMID 35565212, 2022). "Non-BRAF alterations were detected in four tumor samples consisting of CLIP2:NTRK2, KANK1:NTRK2, RAF1:QKI, and KRAS Q61H." (PMID 36163281, 2022). "Mutant BRAF suppresses intratumoral T cells via overexpression of IL-1α and IL-1β by tumor cells, leading to overexpression of PD-L1 and PD-L2 in tumor-associated fibroblasts." (PMID 35703181, 2022). "We confirmed the interaction between endogenous-BRAF and AK2 in BRAF WT-carrying tumor cell lines including NCTC-1469 normal hepatocyte cells." (PMID 35585049, 2022). "Mutations in oncogenic factors including EGFR, ALK, BRAF, or MET, which can change the immunological tumor micro-environment, can enhance tolerance to PD1/PD-L1." (PMID 36499382, 2022). "Using paired normal and tumor DNA from the same patients, we identified and validated a few novel recurrent somatic mutations in LGSOC, in addition to KRAS, BRAF, USP9X, and EIF1AX mutations that have been identified in previous studies." (PMID 36528667, 2022). "Applied alone, the BRAF/MEKi treatment induces immediate and drastic tumor reduction, followed by MRD and development of resistance after approximately four months of continuous administration of the drugs." (PMID 35494017, 2022). "Tumor organoids harboring KRAS, NRAS, BRAF, or PIK3CA hotspot mutations exhibited a relatively higher IC50 and area under the drug response curve (AUC) for cetuximab than organoids without hotspot mutations in these genes." (PMID 34850547, 2022). "Median tumor mutational burden (TMB) was 7.83 mut/Mb (95% CI, 6.85–8.97) in patients with any BRAF alteration (n = 236)." (PMID 35884534, 2022). "A recent study showed that only tumor location in the right colon exhibited a significant correlation with KRAS and BRAF mutational status." (PMID 35681771, 2022). "This approach is similar to that described in the present CASE 1 patient, and confirm the efficacy, rapid action and safety of combined BRAF/MEK inhibitor therapy for tumor debulking at the time of recurrence before repeat surgery or radiotherapy." (PMID 35757402, 2022). "Immunolabelling of cGAS and STING in metastatic CRC was performed and further complemented by histological classification, tumour grade, and KRAS, NRAS, and BRAF mutational status of mCRC." (PMID 36612217, 2022). "However, we can suggest a clue that the de novo difference in the immune profile of BRAF-MT CRC might be associated with treatment responses considering that the tumor tissue used for the multiplex IHC to evaluate the tumor immune profile was obtained before treatment." (PMID 35625987, 2022). "In general, our study provided a novel insight into the full alteration spectrum of BRAF and its implications for treatment and prognosis in diverse tumor types." (PMID 35910024, 2022). "During exploratory data analysis, we noticed that age at operation was strongly correlated with the BRAF status (which was the focus of this study) and a number of baseline or tumor characteristics (which were considered the outcomes)." (PMID 35665338, 2022).
tumor (continued). "The results verified that risk score (HR=1.614 (95% CI: 1.199-2.173), p=0.002) and tumor stage (HR=1.838 (95% CI: 1.228-2.750), p=0.003) were independent risk factors for PFS in the BRAF-mutated cohort." (PMID 35757399, 2022). "The most common tumor types with BRAF CNVs were GBM (81.3%), TGCT (69.1%), ESCA (63.7%), OV (62.9%), adrenocortical carcinoma (ACC) (62.0%), KIRP (61.1%), UCS (59.6%) and LUSC (59.5%)." (PMID 35910024, 2022). "BRAF inhibition with vemurafenib (blue) reduced the tumor growth compared to the sham-treated control mice (black)." (PMID 35406796, 2022). "To visualize the model, we plotted the nomogram of our predictive model based on the five variables: Age, Gender, Focal, BRAF, and Tumor size." (PMID 35784530, 2022). "In our study, the high Fn levels of cancer tissue were associated with key tumor molecular features of CRC, including MLH1 methylation, MSI-high, CIMP-high, KRAS mutation, and BRAF mutation, which were associated with clinical outcomes in CRC." (PMID 36406461, 2022). "One example is the calculation of tumor burden, commonly a prerequisite for many molecular tests, e.g., BRAF (v-raf murine sarcoma viral oncogene homolog B1) mutational assays in cancer patients." (PMID 36361209, 2022). "When comparing the four categories of mutation status: indeterminate, RAS-mutant, BRAF-mutant, and RET/NTRK fusion, all variables were found to be statistically significant (P value < .05), except for sex and AJCC T (tumor size) category." (PMID 35015563, 2022). "This function peaks in the modal position of the primary tumor, in the case of BRAF/MEKi, or in the positions of the BRAF/MEKi resistant states, typically invasive and URC cell populations, in the case of HCT." (PMID 35494017, 2022). "Indeed, particularly in ATC cases, in which a definitive cure is unlikely with standard treatments, the molecular signature of the neoplasia could improve the outcome of patients harboring actionable mutations (i.e., BRAF V600E), as well as in a neoadjuvant setting." (PMID 35463338, 2022). "For 67/77 (87%) patients, baseline analysis of circulating tumor DNA (ctDNA) for KRAS, NRAS, BRAF, and EGFR-extracellular domain S492R mutations was feasible." (PMID 35832541, 2022). "The PLK1 activity controls a polarity checkpoint and compensates for BRAF/MAPK inhibition in CD133(+) tumor cells, suggesting the need for concurrent PLK1 inhibition to improve antitumor activity against a therapy-resistant cell compartment." (PMID 36686797, 2022). "No additional clinically relevant mutations including HER2 overexpression, BRAF V600E mutation, NTRK fusions, and MSI-H tumor types were reported." (PMID 36969746, 2022). "BRAF V600E/K SNV was detectable in 76% and 81% of patients with BRAF V600E/K SNV-positive tumor tissues, respectively." (PMID 35205608, 2022). "As in our study, β-catenin was highly expressed in ACP, especially the presence of the β-catenin nuclear signal of tumor cells that form a “whorled epithelium” structure, while PCP showed a 100% mutation rate of BRAF V600E." (PMID 35707464, 2022). "A preclinical study of CSF-1R inhibition with BRAF inhibitors demonstrated that these therapies complement each other and produce a robust anti-tumour effect." (PMID 35359423, 2022). "In the series of 49 spitzoid neoplasms, 14 lesions were found to have a BRAF fusion, with an average patient age of 24 years, and 50% of these lesions occurring in the extremities." (PMID 35747831, 2022). "In xenografts, targeting DDR with imatinib enhances BRAF inhibitor efficacy, counteracts drug‐induced collagen remodeling, and delays tumor relapse." (PMID 34957688, 2022). "As per clinical guidelines, the assessment of MMR proficiency and the BRAF V600E protein in resected tumours is recommended to inform adjuvant treatment selection." (PMID 35884509, 2022). "At the outset, we explored the mRNA expression pattern of BRAF between tumor samples and adjacent normal tissues in pan-cancer by TIMER2.0." (PMID 35910024, 2022).
tumor (continued). "This study will also analyze cohorts of BRAF mutant tumors and will provide molecular data for each selected tumor entity and a large amount of information on clinical features, treatment history and outcomes." (PMID 36686797, 2022). "Nivolumab is a fully-humanized anti-PD-1 monoclonal antibody that selectively blocks the interaction of PD-1 with its receptors BRAF and programmed death-ligand 2 (PD-L2) and restores T-cell response directed at tumor cells, inducing an anti-tumor effect." (PMID 35911362, 2022). "This has informed several paediatric tumour studies, with BRAF inhibitors since showing promise in pHGG." (PMID 36582791, 2022). "In patient-derived V600EBRAF melanoma cells, treatment to ensure low glutamine levels significantly decreased α-KG levels, which led to the hypermethylation of histone H3, H3K27-mediated tumor dedifferentiation, and resistance to BRAF inhibitor treatment." (PMID 34050894, 2022). "If the tumor shows loss of MLH1 and PMS2 expression, either BRAF mutation analyses or an MLH1 methylation test should be performed." (PMID 35993526, 2022). "A recent study suggests that this immune-evasive state is driven by reactivation of the MAPK pathway in BRAF/MEKi resistant tumours, which also underpins resistance to subsequent immunotherapy, so-called cross-resistance." (PMID 35366166, 2022). "For this reason, the concomitant BRAF and MEK inhibition overcomes the acquired resistance to BRAF inhibitors and potentiates the anti-tumor effects." (PMID 36499450, 2022). "The PI3K/AKT pathway is activated by growth factors binding RTKs, so when BRAF is blocked, tumor cells can overexpress RTK, leading to permanent PI3K/AKT signaling." (PMID 36181568, 2022). "Combination of mutation-specific BRAF inhibitors, and MEK inhibitors show high response rates on mutBRAF MM, however, most patients, acquire resistance resulting in tumor relapse." (PMID 35022419, 2022). "Advances in the genetic assessment of tumor-driving oncogenes allow for a categorization of BRAF mutants into three classes based upon their kinase activity, ability to signal as monomers or dimers, and dependency on RAS signaling [14••]." (PMID 35380338, 2022). "Nevertheless, the drug provides therapeutic benefit in delaying tumor growth and metastatic dissemination in both cell types, albeit with greater potency in BRAF-mutant cells." (PMID 36056964, 2022). "Tumor size, multifocality, and oncocytic changes are easily assessable on a routine pathological examination of postsurgical tissues, and the BRAF status can be determined using IHC or molecular methods in either preoperative biopsy or surgical material." (PMID 35665338, 2022). "In the metastatic setting, elevated pre-treatment CRP and IL-6 were independently associated with shorter PFS and OS, and provided useful information on prognosis in addition to the tumor mutational status (RAS and BRAF)." (PMID 36233472, 2022). "BRAF inhibitors (BRAFi) are highly efficient for treating patients with BRAFV600E mutations, but tumours frequently acquire resistance within a few months." (PMID 36038253, 2022). "This tumor is characterized by the MN1 gene rearrangements (MN1 Proto-Oncogene, Transcriptional Regulator) and shows a BRAF V600E mutation in up to 38% of cases." (PMID 36686797, 2022). "On the other hand, if specific driver mutations are identified (eg, NTRK, ALK, RET, BRAF), new mutation-specific kinase inhibitor should be considered which have been FDA-approved, specifically for TCs or for any tumor type harboring the same molecular target." (PMID 36605433, 2022). "First, it has a historical, retrospective nature, it lacks complete information on some tumor features including TERT and BRAF mutations, and 3% of the patients were lost to follow-up." (PMID 35355557, 2022).
tumor (continued). "The histological parameters were evaluated uniformly in accordance with the latest guidelines and the tumours were screened for two key molecular prognostic parameters (MMR status and BRAF mutation status)." (PMID 35449453, 2022). "Our model was related to tumor TNM staging, pathological staging, and KRAS/BRAF mutational status and played an auxiliary role in the diagnosis and prognosis of CRC." (PMID 35619906, 2022). "For the KRAS, NRAS, and BRAF V600E genes, the concordance rates between the tumor tissue test by PCR and ctDNA test by NGS were 86.4%, 86.4%, and 100%, respectively." (PMID 35280779, 2022). "Accordingly in that study, neither the PERK nor ATF6 branches were involved but interestingly, IRE1α inhibition was required for engaging immunogenic cell death in the BRAF-mutant setting, showing how IRE1α mediates tumor resistance through immune evasion." (PMID 35347108, 2022). "The triple combination of a RAF dimer-selective, a RAF monomer-selective, and a MEK inhibitor (regorafenib plus dabrafenib plus trametinib) was highly effective and well tolerated in multiple BRAF V600E tumor models in vivo." (PMID 36058945, 2022). "More comprehensive analysis with additional CD3+ T cell, regulatory T cell, B cell, and tumor macrophage data can be helpful to better understand the tumor microenvironment of BRAF-MT CRC." (PMID 35625987, 2022). "Tumor cells were then treated with drugs targeting the mutant BRAF/MAPK pathway using BRAFi alone or in combination with MEKi." (PMID 34957688, 2022). "The HCT treatment leads to a mild response initially, but like BRAF/MEKi treatment, induces tumor adaptation." (PMID 35494017, 2022). "Some advocate for the use of the primary tumor, but intertumoral heterogeneity of BRAF between a patient’s primary and subsequent metastatic lesion is still discussed, and a metanalysis has proposed a possible discrepancy rate of approximately 10%." (PMID 36361209, 2022). "While there is a lot of data to explain mechanisms of resistance in other BRAFV600E tumours, comparatively little is known about the mechanisms of BRAF inhibitor resistance in BRAFV600E pHGG." (PMID 36582791, 2022). "In particular, it was found that among the 98 patients showing tumor progression upon initial BRAF ± MEKi therapy, 87 patients (87.8%) also presented with tumor progression during 2L therapy." (PMID 35565212, 2022). "Three of the four tumor clusters display down-regulation of the MAPK pathway (gene set taken from the Hallmark MSigDB), precluding the use of BRAF/MEK inhibitor treatment." (PMID 35658001, 2022). "Starting first with HCT and then using BRAF/MEKi, however, was a better strategy that significantly delayed resistance and also reduced the tumor load by combining the advantages of the two treatments." (PMID 35494017, 2022). "CRC patients with RAS and BRAF WT both on tumor tissue and on ct-DNA at baseline receiving rechallenge with cetuximab were eligible for our analysis." (PMID 35530345, 2022). "In tumor cells with mutations in KRAS or BRAF, mtHSP70 facilitates the interaction between PP1α and MEK1/2, which modulates MEK/ERK signaling activity, thereby promoting tumor cell proliferation." (PMID 35180892, 2022). "We further analyzed the correlation between the PRM and clinical features (gender, age, BRAF V600E, IDH, KPS, MGMT, and original subtype) and tumor mutation burden (TMB)." (PMID 35783263, 2022). "Previous studies have identified number of tumor foci, TSH level, and BRAF mutation as predictors of bilateral multifocal disease." (PMID 36686467, 2022).
tumor (continued). "Individuals with high risk of LS based on tumour tests (here and below, dMMR/MSI, plus BRAF V600E and/or MLH1 promoter hypermethylation tests where needed) should be referred for genetic counselling and germline genetic testing as appropriate." (PMID 35509103, 2022). "This combination was well-tolerated and had anti-tumor activity equivalent to current first-line treatments such as ICIs or a BRAF/MEK TKIs." (PMID 35954441, 2022). "Because tumor cells of regional lymph-node resections and skin lesions shared a similar appearance, CNNTB was subsequently tested on lymph-node metastases with a BRAF mutational status (n = 5)." (PMID 36361209, 2022). "Next, we examined differential gene expression when the HP primary tumor and metastatic samples were subdivided into their particular genomic subtypes (BRAF, RAS, triple WT and NF1)." (PMID 35560144, 2022). "The applicability of our model for tumor therapeutics was demonstrated by treatment with a commonly used v-raf murine sarcoma viral oncogene homolog B (BRAF) inhibitor vemurafenib." (PMID 36175453, 2022). "Combination therapy can be used for limiting adaptive feedback, similar to the experience with v-raf murine sarcoma viral oncogene homolog B1 (BRAF) inhibitors; this is essential to maximize the durability of response in each tumour type." (PMID 36632627, 2022). "We examined the potency of tumor-agnostic therapy for fusion-driven cancer, by assessing the effect of BRAF inhibitor in RAF1 fusion-driven cancer." (PMID 36033527, 2022). "BRAF will continue to be activated and the cell will continue overexpressing the pathway that leads to tumor cell proliferation, survival, and metastasis." (PMID 35044091, 2022). "For example, patients having tumours with only one driver event were unlucky that this event happened (by chance) in one of the most crucial genes such as BRAF." (PMID 35030162, 2022). "For the combination therapy, BRAF/MEKi then HCT, we observe a later time-point for the re-establishment of the initial tumor volume, in comparison to BRAF/MEKi only, but still resulted in a significant increased tumor growth rate." (PMID 35494017, 2022). "In tumor cells bearing BRAFV600E mutants, the mutated form can dimerize with BRAFV600E, wild-type BRAF and wild-type CRAF, leading to MAPK pathway reactivation." (PMID 36698391, 2022). "Mutations usually occur in the serine/threonine kinase B-Raf proto-oncogene (BRAF) within the RAS/MAPK pathway, and specific mutations can be associated with a certain tumor type." (PMID 35884462, 2022). "Nonetheless, since mTmG faithfully detected contiguous mG+ progenies of normally dividing follicular cells, we chose this reporter strain for clonal analysis of BRAF-induced tumor development." (PMID 34379110, 2022). "It evaluates the presence of KRAS, NRAS, and BRAF mutations, nodal status, CEA/CA19-9 levels, and the modified Tumor Burden Score to predict cancer recurrence." (PMID 36428606, 2022). "Similar to the archival tumor samples, mutations in PDGFRA or BRAF were rare (n = 2 and n = 0, respectively)." (PMID 35050442, 2022). "Many studies have reported a high concordance between tumor and plasma in the detection of KRAS and BRAF mutations using ddPCR." (PMID 36248993, 2022). "Like the proximity score, high density score was associated with proximal tumour location (P = 0.003), low disease stage (P = 0.0002), absence of lymphovascular invasion (P = 0.0004), MMR deficiency (P < 0.0001) and BRAF mutation (P = 0.001)." (PMID 35449453, 2022).